IL4 (interleukin 4)
Diseases named in the same sentence as IL4 in open-access papers (continued):
Sharing a sentence is not in itself a finding about the gene and the disease.
membranous nephropathy (3 papers, 2016 to 2022). "As previously reported, serum IL-4 levels are associated with disease severity in patients with membranous nephropathy." (PMID 35585990, 2022). "Significantly higher frequency of CD4+/CXCR5+, CD4+/CXCR5+/ICOS+ and CD4+/CXCR5+/PD-1+ TFH cells, and higher serum levels of IL-17A, IFN-γ, IL-2, IL-10, IL-4 and IL-21 were detected in hepatitis B virus-associated membranous nephropathy patients compared to the healthy controls." (PMID 28770269, 2018). "In contrast, the peripheral Th1/Th2 ratio (IFN-γ/IL-4 ratio) was significantly lower in membranous nephropathy when compared to the other entities." (PMID 26989679, 2016).
memory impairment (3 papers, 2016 to 2025). "Three studies measured IL-4 and IL-10, and only one reported an increase in IL-10 (together with other cytokines) that was associated with memory impairment." (PMID 41155372, 2025). "In addition, dural meningeal CD4 + T cells produce IL4 at steady-state and both IL4−/− mice and IL4 receptor silencing on GABAergic neurons of the hippocampus and the retrosplenial cortex recapitulate memory impairment." (PMID 38291415, 2024).
metastatic melanoma (3 papers, 2021 to 2026). A melanoma that has spread from its primary site to another anatomic site. "Stimulation with IL-4 enhances the NK cell cytotoxicity against metastatic melanoma patients." (PMID 41596411, 2026).
microcephaly (3 papers, 2021 to 2023). A congenital or acquired developmental disorder in which the circumference of the head is smaller than normal for the person's age and sex. "In this study, TREM1 rs2234246 and IL4 rs224325 in mothers infected with ZIKV during pregnancy was found to be associated with the occurrence of CZS microcephaly and the SNP CXCL10 rs4508917 and CXCL8 rs4073 in their children with presence of CZS microcephaly." (PMID 36859461, 2023). "When only cases with microcephaly were compared with controls, IL-4 was significantly higher among cases." (PMID 33875756, 2021). "Along with the significant increase in IL-4 levels in CSF of microcephalic neonates described here, it is possible that an exacerbated activity of antibody-producing cells driven by this cytokine may take place in ZIKV-associated microcephaly." (PMID 33875756, 2021). "In the canonical coefficient analysis between controls and those exposed to ZIKV without microcephaly, we found that IL-1β, IL-3, IL-4, IL-7 and EOTAXIN (CCL11) were the top CSF markers in our model." (PMID 33875756, 2021). "When cases with and without microcephaly were compared IL-4 and TNF-β were significantly higher and MCP1 (CCL2) was significantly lower among microcephalic cases." (PMID 33875756, 2021). "Conversely, ZIKV-exposed participants without microcephaly displayed a general trend to decrease concentrations of inflammation mediators as IL-2, IL-4, IL-12p40, IL-12p70, TNF-α, TNF-β, IFN-γ, and the growth factors GCSF and EGF." (PMID 33875756, 2021).
monocytic leukemia (3 papers, 2023 to 2025). "Dendritic cells can be derived from human peripheral blood or THP-1, a human monocytic leukemia-derived immortalized cell line, using granulocyte-macrophage colony-stimulating factor GM-CSF and interleukin 4 (IL-4)." (PMID 39853027, 2024). "In addition, U937, a human monocytic leukemia cell line, was treated with phorbol-12-myristate-13-acetate and interleukin (IL)-4 to induce an M2 macrophage phenotype and analyzed markers for M2 polarization." (PMID 40604704, 2025). "The human monocyte leukemia cell line, THP-1, was differentiated into macrophages using PMA and then polarized into M2 macrophages by IL-4 treatment." (PMID 36864028, 2023).
narcolepsy (3 papers, 2018 to 2024). A sleep disorder characterized by a tendency for excessive sleepiness during the day which occurs even after adequate sleep in the nighttime. "Although increased levels of DN T-cells in narcolepsy have not been demonstrated, patients with narcolepsy display elevated concentrations of cytokines, including IL-4 and IFN-γ." (PMID 39544989, 2024).
nasal obstruction (3 papers, 2021 to 2025). "Elevated WBC may also imply increased levels of cytokines like IL-4, IL-5, and IL-13, resulting in more severe nasal obstruction, rhinorrhea, and loss of smell." (PMID 41473511, 2025). "IL-4 in nasal secretions was positively correlated with nasal obstruction (r = 0.4492, P = 0.0036)." (PMID 39525400, 2024).
non-alcoholic fatty liver disease (3 papers, 2021 to 2024). "MAIT cells promote M2 polarization of macrophages in non-alcoholic fatty liver disease (NAFLD) by the production of regulatory cytokines (high production of IL-4, but reduced IFN-γ and TNF levels)." (PMID 36875139, 2023).
obstructive sleep apnea (3 papers, 2020 to 2021). "After the analysis of the levels of pro and anti-inflammatory markers (IL-1β, IL-4, IL-6, IL-8, IL-10, Il-15, TNF-α, CRP, α1-GP) in the tonsils, we observed higher levels of markers IL-8 and IL-10 in pediatric patients with obstructive sleep apnea syndrome." (PMID 30213594, 2020). "Verify the levels of the inflammatory markers, IL-1β, IL-4, IL-6, IL-8, IL-10, IL-15, TNF-α, CRP and α1-GP, in the tonsils of children with and without obstructive sleep apnea syndrome." (PMID 30213594, 2020).
oral squamous cell carcinoma (3 papers, 2023 to 2024). "Previously study have shown that JMJD6 expression was higher in human oral squamous cell carcinoma by inducing interleukin 4 transcription and binding to its promoter region." (PMID 37488513, 2023). "YBX1 was reported to promote IL-4 expression in oral squamous cell carcinoma cells." (PMID 38575607, 2024). "In addition, YBX1 promoted IL-4 expression in oral squamous cell carcinoma cells." (PMID 38575607, 2024).
pancreatic ductal adenocarcinoma (3 papers, 2022 to 2025). An infiltrating adenocarcinoma that arises from the epithelial cells of the pancreas. "In a large cohort of patients with pancreatic ductal adenocarcinoma (PDAC), basophils expressing interleukin-4 (IL-4) were identified in the tumor-draining lymph nodes (TDLN; the main sites of antitumor immunity development)." (PMID 40136652, 2025). "For example, MCP3/CCL7, IL4 and IL3 have been previously shown to be involved in the tumour microenvironment of pancreatic ductal adenocarcinoma and play a complex role in the regulation of tumour-promoting inflammation." (PMID 35064782, 2022).
Parkinsonism (3 papers, 2018 to 2021). Characteristic neurologic anomaly resulting from degeneration of dopamine-generating cells in the substantia nigra, a region of the midbrain, characterized clinically by shaking, rigidity, slowness of movement and difficulty with walking and gait. "No cytokine was a specific marker for parkinsonism, but TNF-α, CPP, IL-1β, IL-4, and IL-6 may be useful for early differentiation of atypical parkinsonism to PD." (PMID 30390673, 2018).
periapical granuloma (3 papers, 2016 to 2024). Chronic nonsuppurative inflammation of periapical tissue resulting from irritation following pulp disease or endodontic treatment. "On estimation of IL-21 levels in periapical granulomas, it was demonstrated that IL-21 along with IL-17A, TNF-α (tumour necrosis factor-α), and IFN-γ were higher in active periapical granulomas, while IL-4, IL-9, IL-10, and IL-22 were higher in inactive periapical granulomas." (PMID 26998377, 2016). "There is extensive research with inflammatory markers (e.g., Galectin 1 and 7, intercellular adhesion molecular-1, degranulated mast cells, TGFb, IFNd, TNFa, IL4, IL6), observing differences in expression between periapical cysts and periapical granulomas." (PMID 39691380, 2024).
pneumococcal pneumonia (3 papers, 2011 to 2025). A febrile disease caused by STREPTOCOCCUS PNEUMONIAE. "As we previously reported, IL-4 levels in the lung were still a significant factor for the risk of pneumococcal pneumonia in our mouse model, adjusting for the role of IL-17 and OVA sensitization/challenge." (PMID 22164165, 2011). "This reduced risk of pneumococcal pneumonia in OVA-sensitized/challenged mice was minimally accounted for by IL-17 levels in lung, but IL-4 levels in lung were more significantly associated with the risk of pneumococcal pneumonia than IL-17." (PMID 22164165, 2011). "IL-17 levels result in a much smaller impact on the risk for pneumococcal pneumonia, compared to IL-4 levels." (PMID 22164165, 2011). "Therefore, while Th2 cytokines such as IL-4 are associated with a risk of bacterial pneumonia in mice, how allergic sensitization provides a protective effect against pneumococcal pneumonia in mice is not well understood." (PMID 22164165, 2011). "However, IL-4 levels in the lung are still more important for determining the risk of pneumococcal pneumonia than IL-17 and allergic sensitization." (PMID 22164165, 2011). "We previously reported that a T-helper 2 (Th2) predominant immune response (e.g., IL-4) to OVA sensitization was a significant risk factor for pneumococcal infection, whereas allergic sensitization itself was protective against pneumococcal pneumonia." (PMID 22164165, 2011). "Therefore, adjusting for the impact of IL-4 and OVA sensitization/challenge on the risk on pneumococcal pneumonia, IL-17 minimally influenced the risk of pneumococcal pneumonia." (PMID 22164165, 2011). "The mean level (± standard error) of IL-4 in lung homogenates among mice with pneumococcal pneumonia was 1.09 ± 0.14 pg/mL whereas that among mice without pneumococcal pneumonia was 0.67 ± 0.06 pg/mL (P = 0.0037)." (PMID 22164165, 2011).
polyposis (3 papers, 2017 to 2019). "Our study shows the effect of the RP1 allele of IL-4 on the susceptibility of polyposis formation in patients with CRSwNP." (PMID 31650822, 2019). "It is quite likely that, in the APC Min/+ model of polyposis, IL-33 promotes polyposis formation via Th2 cytokines IL-4 and IL-13 as well as inflammatory cytokine IL-6, which facilitate mast cell function." (PMID 29499051, 2018).
prediabetes (3 papers, 2016 to 2023). "In conclusion, circulating inflammatory mediators, hs-CRP, IgE, IL-4, IL-10, and tryptase, were positively associated with prediabetes or T2DM." (PMID 27478850, 2016). "Serum tryptase was associated with prediabetes (OR: 1.53 (1.01–2.32, 95% CI), P = 0.044) before adjustment and (OR: 1.63 (1.02–2.61, 95% CI), P = 0.041) after adjustment by multivariable + IL-4, compared with NGG." (PMID 27478850, 2016). "We concluded that Hs-CRP, IgE, IL-4, IL-10, and tryptase were positively associated with prediabetes or T2DM." (PMID 27478850, 2016). "But in this paper, our data indicated that tryptase was mildly associated with prediabetes (OR: 1.63 (1.02–2.61, 95% CI), P = 0.041) after adjustment by multivariable + IL-4, compared with NGG, which could be explained for the synergistic effect of IL-4." (PMID 27478850, 2016). "After the adjustment for waist circumference the significance persistent for IL-4, IP-10, TNF-α, RANTES, CD40L and VEGF, indicating that inflammation is an independent hallmark in prediabetes." (PMID 30143687, 2018). "Our data showed increased levels of CRP, IL-4, IL-10, and tryptase in prediabetes subjects and increased levels of CRP, IL-4, and IL-10 in T2DM subjects compared with normal glucose subjects." (PMID 27478850, 2016). "Our data showed increased levels of hypersensitivity C-reactive protein (hs-CRP), interleukin (IL-4), IL-10, and tryptase in prediabetes subjects and hs-CRP, immunoglobulin E (IgE), IL-4, and IL-10 in T2DM subjects." (PMID 27478850, 2016). "No significant variation of cytokines was observed between prediabetes and control group for IL-6, IL-10, IL-17A, IL-4, IL-8, IFN-γ, and TNF-α." (PMID 37457235, 2023).
prion disease (3 papers, 2013 to 2026). A transmissible disease that is caused by a protein that is able to induce abnormal folding of normal cellular proteins, leading to characteristic spongiform brain changes, which are associated with neuronal loss without an inflammatory response. "Conversely, TNF-α, IL-4, IL-6, IL-12(p40), IL-12(p35), IL-13, and transforming growth factor-β1 are probably not pathogenic in prion disease because knockout of these cytokines did not change the disease course of prion-inoculated mice." (PMID 24219883, 2013).
prostate tumor (3 papers, 2021 to 2025). "Clinical observations further support these findings, revealing IL-4’s role in fostering prostate tumor cell survival by impeding apoptosis." (PMID 40507238, 2025). "Our data demonstrated that in the context of prostate tumor models or IL4 stimulation, primary MDMs expressed an immunosuppressive or M2-like phenotype." (PMID 39414902, 2024).
psychological distress (3 papers, 2022 to 2024). "In conclusion, we found that psychological distress was associated with the cytokines IL-2, IL-4, IL-5, IL-10, IL-12, TNF-α, and IFN-γ." (PMID 36405903, 2022). "However, psychological distress was significantly associated with the plasma cytokines IL-2, IL-4, IL-5, IL-10, IL-12, TNF-α and IFN-γ." (PMID 36405903, 2022). "However, cytokine levels can be altered by infection and cancer treatment, and an extended follow‐up is required to assess the dynamic course of IL‐1β, TNF‐α, and IL‐4 with psychological distress." (PMID 36965094, 2023). "A recent study found that higher psychological distress indirectly predicted worse cognition through higher levels of IL-1β, TNF-α, and IL-4." (PMID 38840166, 2024). "The link between psychological distress and cognitive function as measured by the MMSE was also mediated by IL‐1β, TNF‐α, and IL‐4 (effect size: 26%, 25%, and 24%)." (PMID 36965094, 2023). "The indirect effect size of psychological distress on cognitive function through IL‐1β, TNF‐α, and IL‐4 were 26%, 25%, and 24%, respectively." (PMID 36965094, 2023). "In all mediation models, the A path on behalf of the relationship between psychological distress and cytokine levels (IL‐1β, TNF‐α, and IL‐4) was significant and positive (=4.80, =4.70, =3.25, respectively; <0.05)." (PMID 36965094, 2023). "Psychological distress is common and almost accompanied by the whole process of cancer, and its relationship with cytokines deserved further study though the indirect effect size of psychological distress on cognitive function through IL‐1β, TNF‐α, and IL‐4 is limited." (PMID 36965094, 2023). "Using PROCESS, we investigated whether psychological distress predicted cognitive function based on MMSE through IL‐1β, TNF‐α, and IL‐4." (PMID 36965094, 2023). "The indirect effect of psychological distress via IL‐1β, TNF‐α, and IL‐4 on the MMSE was significant and negative (=−0.34, =−0.32, =−0.32, respectively; 95% CI [−0.59 to −0.17], [−0.52 to −0.16], [−0.54 to −0.13])." (PMID 36965094, 2023).
pyometra (3 papers, 2019 to 2025). "(2014), TNF‐α, IFN‐γ, IL‐2, IL‐4 and IL‐10 cytokine concentrations were found to be high in dogs with pyometra." (PMID 39792082, 2025). "However, further studies using more sensitive assays are needed to confirm the role of IL-4 in pyometra." (PMID 40584120, 2025). "Furthermore, the level of IL-4 is significantly greater in bitches with pyometra compared with the females in dioestrus, anoestrus and pregnancy." (PMID 33224295, 2019). "This study aimed to evaluate retinal vascular calibers in bitches with pyometra-induced SIRS (P-SIRS) and explore correlations between retinal measurements and hematological, biochemical, vascular endothelial growth factor (VEGF), and interleukin-4 (IL-4) levels." (PMID 40584120, 2025).
rosacea (3 papers, 2020 to 2025). A chronic erythematous skin disorder that affects the face. "IL-4 and IL-13, although classically linked to Th2 responses, have also been detected in rosacea lesions and contribute to chronic inflammation and fibrosis." (PMID 40725084, 2025). "Future studies will be necessary in order to assess specific risk factors and the mechanism responsible for the development of rosacea-like folliculitis in a subset of patients following IL-4/IL-13 inhibition." (PMID 32344789, 2020). "Adaptive T cell–derived cytokines IFNG, IL17A, IL17F, and IL22 were significantly overexpressed in lesional rosacea skin, while IL4 was either undetectable or not increased." (PMID 36633910, 2023).
sarcoma (3 papers, 2019 to 2025). A usually aggressive malignant neoplasm of the soft tissue or bone. "We used a panel of EwS, RMS and OS pediatric sarcoma cell lines to test six cytokines, used for monocyte differentiation and DC maturation (IL-4, GM-CSF, IL-1β, IL-6, TNF and PGE2), for their ability to induce cancer cell immunogenicity and sensitivity to tumor antigen-specific T cells." (PMID 39723214, 2024). "In contrast to TNF and IL-1β, the other tested monocyte maturation mediators, including IL-4, GM-CSF, IL-6 and PGE2, weakly affected expression of immunogenic surface markers on pediatric sarcoma cells." (PMID 39723214, 2024). "We observed that TNF and IL-1β upregulated MHC class I, ICAM-1 as well as CD83 and PD-L1 on the surface of pediatric sarcoma cell lines, while IL-4, GM-CSF, IL-6 and PGE2 failed to induce respective effects." (PMID 39723214, 2024). "Levels of IL-1β, IL-4, IL-6, CXCL5, CXCL12, CXCL14, MIF, IGF-1, TGFβ-1, and CCL21 were increased in one or more sarcoma cohorts compared with controls, and levels of IL-15 and IL-16 were significantly lower in one or more sarcoma cohorts compared to healthy controls." (PMID 41008853, 2025).
Sézary syndrome (3 papers, 2006 to 2021). "Cutaneous lesions of MF are characterised by an epidermal Th1-type cytokine profile consisting of interleukin-2 and IFN-γ, whereas a type 2 cytokine production profile, consisting of IL-4, is more likely to occur in Sézary syndrome, the erythrodermic variant of MF." (PMID 16495924, 2006). "To evaluate whether NLRP3 may regulate IL-4 expression in malignant CD4+ T cells, we used the HTB-176 cell line isolated from the peripheral blood of a patient with Sézary syndrome." (PMID 34220814, 2021).
skin cancer (3 papers, 2016 to 2018). "Studies in genetically modified mice and in human tumors found that altered expression of selected pro- (MCP-1, IFN-γ) and/or anti-inflammatory cytokines (IL-4, IL-10, and TGF-β1) had a crucial role in the promotion of gastric, colorectal, liver, breast, and skin carcinoma development." (PMID 28053372, 2016).
Ss (3 papers, 2016 to 2019). "We hypothesized that Ss infection would be associated with alterations in memory T cell subset distribution, alterations that could be reflective of changes in IL-2, IL-4, IL-7, IL-9 and IL-15." (PMID 29795573, 2018). "This confirms our previous data demonstrating elevated IL-4 and IL-9 responses in Ss infection and its reversal following anthelmintic therapy." (PMID 29795573, 2018). "In addition, it was previously reported Type 1 cytokines were significantly reduced and IL-4 were significantly enhanced in both LTB and active TB co-infected with Ss infection." (PMID 30897083, 2019).
systemic inflammatory response syndrome (3 papers, 2011 to 2024). SIRS is a serious condition related to systemic inflammation, organ dysfunction, and organ failure. "In systemic inflammatory response syndrome (SIRS), anti-inflammatory cytokines (IL-10, IL-4, IL-13, and PGE2) balance pro-inflammatory cytokines, a process known as the “cytokine storm”, leading to excessive inflammation." (PMID 39337069, 2024).
trypanosomiasis (3 papers, 2011 to 2022). Infection with protozoa of the genus trypanosoma. "Moreover, interleukin-4 (IL-4), IL-10 and Transforming Growth Factor-β (TGF-β), which are potent arginase inducers, are enhanced in experimental trypanosomiasis." (PMID 21408057, 2011).